STAT3 (signal transducer and activator of transcription 3)
Diseases named in the same sentence as STAT3 in open-access papers (continued):
Sharing a sentence is not in itself a finding about the gene and the disease.
hepatocellular carcinoma (continued). "IL-6 can activate STAT3 signal pathway to drive hepatocyte replication and promote the occurrence of hepatocellular carcinoma." (PMID 35096588, 2021). "Ursolic acid has been shown to suppress colon cancer and hepatocellular carcinoma by inhibiting STAT3 signaling, whereas paeoniflorin exerted anti-diabetic effects and suppressed glioma cell growth by targeting STAT3." (PMID 33967784, 2021). "Recent studies demonstrate that there is a possible crosstalk between the BMP/SMAD and the IL-6 mediated JAK/STAT3 pathway at inflammation in hepatoma cell lines and primary mouse hepatocytes." (PMID 33835366, 2021). "IL-6 has been studied extensively in VM promotion and crosslinked to STAT3 in human hepatocellular carcinoma." (PMID 34055597, 2021). "Overall, these findings indicated that the activation of PI3-K, ERK, and STAT3 pathways mediated by LASP1 was responsible for vimentin protein expression in HBX-positive hepatoma cells." (PMID 33722250, 2021). "Luteolin has been reported to promote the degradation of phosphorylated STAT3 in human hepatoma cells." (PMID 33392396, 2021). "It was also reported that IL-17A activates the IL-6/STAT3 signal pathway followed by cell proliferation in hepatocellular carcinoma." (PMID 34445513, 2021). "In hepatoma cells, baicalein can restore the antitumor activity of T cells by reducing the activity of STAT3 and downregulating the expression of PD-L1 induced by IFN-γ." (PMID 34326876, 2021). "In mice, the conditional deletion of Ptpn2 can also contribute to the development of skin cancers, as well as hepatocellular carcinomas, due to the promotion of STAT3 signalling." (PMID 34884538, 2021). "In hepatocellular carcinoma cells, sorafenib inhibits STAT3 activity by dephosphorylating STAT3 and leads to the downregulation of Mcl-1." (PMID 34277607, 2021). "The experiments revealed that overexpression of miR-637 in some hepatocellular carcinoma cell lines gave rise to a reduction in proliferation of cancer cells by regulation of signal transducer and activator of transcription 3 (STAT3)." (PMID 33541259, 2021). "Our result is similar to a previous study which reported that β-escin (a compound present in the medicinal plant Aesculus hippocastanum) induced cytotoxicity in human hepatocellular carcinoma via the suppression of STAT3 activation." (PMID 34078370, 2021). "First, the effect of cryptolepine on the IL-6/STAT3 pathway in human hepatoma cells (HepG2 cells) was screened using the Cignal Finder Multi-Pathway Reporter Array." (PMID 34078370, 2021). "For example, IL-17 activates the IL-6/STAT3 signal pathway in the proliferation of hepatitis B virus-related hepatocellular carcinoma." (PMID 33859718, 2021). "On the one hand, PI3-K, ERK, and STAT3 signal pathways were involved in the upregulation of vimentin mediated by LASP1 in HBX-positive hepatoma cells." (PMID 33722250, 2021). "Given that IL-6 plays a key role in regulating inflammatory hepcidin expression by activating STAT3, we examined the roles of DP in the expression of JAK2, p-JAK2, STAT3, and p-STAT3 in HepG2 hepatoma cells treated with IL-6." (PMID 33488942, 2021). "In the study by Shuai Wang, the NEAT1 paraspeckle promoted the progression of human hepatocellular carcinoma by increasing IL-6/STAT3 signalling." (PMID 33546665, 2021). "The activation of STAT3 by IL-6 results in macrophage polarization into M1 macrophages, which are involved in the development of hepatocellular carcinoma (HCC)." (PMID 34576053, 2021). "Nuclear factor-kappa B in the NF-kB/IL-6/STAT3 pathway plays an important oncogenic role in cancers that arise from chronic inflammation such as hepatocellular carcinoma." (PMID 35154607, 2021). "The tumorigenesis, invasion, and metastasis of hepatocellular carcinoma are also related to STAT3 activation." (PMID 33435880, 2021).
hepatocellular carcinoma (continued). "This polyisoprenylated benzophenone extracted from Garcinia indica was used by Sethi and collaborators as an inhibitor of STAT3 acetylation and as a possible treatment for human hepatocellular carcinoma (HCC)." (PMID 34440160, 2021). "Circ-LRIG3 interacts with EZH2 and STAT3 to facilitate EZH2-induced STAT3 phosphorylation, resulting in the malignant progression of hepatocellular carcinoma." (PMID 34485151, 2021). "Nuclear factor-erythroid 2 like 1 (NFE2L1), also known as NRF1, is another key transcription factor that can promote hepatoma cell invasiveness via the STAT3/NFE2L1/STX12 axis." (PMID 34440674, 2021). "The therapeutic inhibition of either pro-tumorigenic STAT3 or NF-κB signaling is currently being tested in clinical trials, for several cancer types including hepatocellular carcinoma (HCC), colorectal, prostate, breast cancer and leukaemia." (PMID 33802972, 2021). "In our previous report, BS downregulated the PD-L1 expression of hepatocellular carcinoma cells and inhibited tumorigenesis by blocking the STAT3 pathway in a mouse model." (PMID 34540892, 2021). "Subsequently, we showed that STAT3 was increased in five hepatocellular carcinoma cells compared with one healthy human liver cell." (PMID 33292166, 2020). "Astoundingly, garcinol hindered the development of human hepatocellular carcinoma xenograft tumors in athymic nu/nu mice by impairing STAT3 activation." (PMID 32545187, 2020). "The results suggested that hsa_circ_0006916 acted as a sponge of miR-337-3p and had an important functional use in the regulation of STAT3 levels in hepatocellular carcinoma cells." (PMID 33292166, 2020). "LncRNA NEAT1-containing paraspeckles also stimulate interleukin 6 (IL-6)-mediated hepatocellular carcinoma development by the nuclear entrapping of IL-6/signal transducer and activator of transcription 3 (STAT3) inhibitors." (PMID 32429086, 2020). "IL-6 secreted by TAMs is highly correlated with the occurrence and development of hepatic carcinoma via activating STAT3 pathway." (PMID 31903134, 2020). "In hepatocellular carcinoma cells (HepG2), evodiamine effectively hindered constitutive and IL-6-induced activation of STAT3 (Tyr705) phosphorylation." (PMID 32545187, 2020). "The proapoptotic and antiproliferative impacts of garcinol in hepatocellular carcinoma were mediated through inhibition of the STAT3 signaling pathway." (PMID 32545187, 2020). "For example, PTPN2 deletion in the liver can facilitate the STAT‐3‐dependent development of hepatocellular carcinoma in obesity." (PMID 31803974, 2020). "Previous reports showed that IL-17A-induced STAT3 activation promotes tumor progression and angiogenesis in hepatocellular carcinoma and non-small-cell lung cancer, respectively." (PMID 32492770, 2020). "Treating human hepatocellular carcinoma cells with tocilizumab, a humanized anti-IL-6 receptor antibody, or knockdown of STAT3 in these cells attenuated the growth of CD44+ cancer stem cells that were induced by TAMs." (PMID 32283687, 2020). "MAGEC2 promotes metastasis in human hepatocellular carcinoma cells by reducing the ubiquitin-mediated proteolysis of p-STAT3." (PMID 32116696, 2020). "Immunohistochemistry (IHC) demonstrated that STAT3 was substantially overexpressed in hepatocellular carcinoma tissues." (PMID 33292166, 2020). "JAK1 mutations have been identified in hepatocellular carcinoma (HCC) patient tumors; patient-derived xenografts with JAK1 S703I mutations had elevated levels of phosphorylated STAT3 and STAT5." (PMID 33521321, 2020). "Herein, we observed that expression of STAT3 was high in hepatocellular carcinoma tissues and cell lines." (PMID 33292166, 2020). "Our recent study reported that long non-coding RNA TPTEP1 inhibits hepatocellular carcinoma progression by interacting and suppressing STAT3 phosphorylation." (PMID 32123532, 2020).
hepatocellular carcinoma (continued). "In this study, we found pSTAT3 can be activated by OF, however, when we combined the STAT3 inhibitor with OF, we observed synergistic effect on inhibiting hepatoma cell proliferation." (PMID 33377648, 2020). "The JAK2/STAT3 pathway is activated downstream B7-H3-induced signaling which is in agreement with reports of the B7-H3 role in multiple myeloma, hepatocellular carcinoma, and glioma cell lines." (PMID 33426073, 2020). "We proved that OF binds to ASGR1/2 receptors on hepatoma cell, we also provided strong evidence that OF activates phosphorylation of STAT3, and then pSTAT3 will bind to P1 promoter of HNF4A, transcriptionally regulates the level of HNF4A, P1 isoform." (PMID 33377648, 2020). "By reducing Akt and STAT3 phosphorylation, 5,7-dihydroxyflavone significantly suppressed the growth of human hepatocellular carcinoma (HepG2) tumor xenografts." (PMID 32545187, 2020). "Our data suggest a novel hsa_circ_0006916/miR-337-3p/STAT3 axis in hepatocellular carcinoma, and provide a new target for treatment." (PMID 33292166, 2020). "Overexpression of UCK2 increased MMP2/9 expression and further activated Stat3 signaling, mediating the metastasis of hepatocellular carcinoma cells." (PMID 32894095, 2020). "In one study, STAT3 inhibition downregulated the expression of Bcl-xL, cyclin D1 and survivin, and induced apoptosis in a hepatocellular carcinoma xenograft model." (PMID 32872659, 2020). "Activation of STAT3 and survivin expression also confers resistance to chemotherapeutic agents (5-FU or cisplatin) in gastric cancer, hepatocellular carcinoma, NSCC and ovarian cancer." (PMID 32872659, 2020). "In conclusion, our findings indicated a hsa_circ_0006916/miR-337-3p/STAT3 axis in hepatocellular carcinoma progression for the first time." (PMID 33292166, 2020). "hIL-6 induced STAT3 phosphorylation also in HepG2 cells, a human hepatocellular carcinoma cell line." (PMID 32365119, 2020). "A previous study showed that CK regulated STAT3 to induce endoplasmic reticulum stress in human hepatoma cells, promoting hepatoma cell apoptosis and inhibiting proliferation." (PMID 33363466, 2020). "In particular, high secretion of IL6 in MSCs can activate the IL6/STAT3 signaling pathway and promote cell invasion in hepatocellular carcinoma cells." (PMID 32560387, 2020). "Another anti-inflammation and anti-tumor gene, heme oxygenase-1 (HO-1) is induced by Interleukin 6 (IL-6) through the IL-6/Janus kinase (JAK)/STAT3 pathways in hepatoma cells." (PMID 32545625, 2020). "Moreover, morusin treatment also suppresses the metastatic capacity of the human hepatoma SK-Hep1 cell line, which may be biochemically associated with inhibition of STAT3 and NF-κB followed by the reduction of the expression of metastatic markers, such as vimentin, α2- and β1-integrins." (PMID 32906784, 2020). "LncARSR was up-regulated in liver cancer stem cells (CSCs) and promoted hepatocellular carcinoma cells dedifferentiation and liver CSCs separation by modulating STAT3 signaling." (PMID 31892841, 2020). "Metastasis of human hepatocellular carcinoma and inhibition ofgrowth was found by antisense oligonucleotide targeting of STAT-3." (PMID 32167126, 2020). "MiR-637 directly targets leukemia inhibitory factor (LIF), which suppresses the tumorigenesis of hepatocellular carcinoma by interfering with the transcription factor Stat3 signaling pathway." (PMID 32264877, 2020). "By subduing the bioavailability of insulin-like growth factors (IGFs), it also decreased the level of IGF-mediated phosphorylated-STAT3 proteins in hepatocellular carcinoma cells." (PMID 32545187, 2020).
hepatocellular carcinoma (continued). "The detrimental effect of EGCG on the phosphorylation of STAT3 has been described in hepatocellular carcinoma cell lines and colorectal carcinoma." (PMID 32326395, 2020). "In HBx induced hepatocellular carcinoma mice model, IL-6/STAT3, and Wnt/β-catenin signaling pathways are constitutively activated." (PMID 33234142, 2020). "Recently, research has revealed that in hepatocellular carcinoma, it exerts its anti-angiogenesis effect though suppressing the STAT3/HIF-1α/VEGF signaling network." (PMID 30871059, 2019). "In hepatocellular carcinoma (HCC), tumor-associated macrophages promote CD44+ stem-like cell expansion, and IL-6/STAT3 signaling inhibition using Tocilizumab (TCZ) inhibits this expansion." (PMID 30804456, 2019). "CT inhibited the proliferation of mouse hepatoma (Hepa1-6) cells in vitro by inducing Hepa1-6 cells apoptosis through the JAK2/STAT3 signaling pathway." (PMID 31161238, 2019). "In addition, HBV infection is the main cause of hepatocellular carcinoma (HCC) and drives increased IL-23 production by inducing STAT3 phosphorylation to confine hepatocyte nuclear factor 4 alpha (HNF4α)." (PMID 31443406, 2019). "Several reports described the influence of STAT3 in the tumor development of colorectal adenocarcinoma, hepatocellular carcinoma, multiple myeloma, glioblastoma, and prostate, head, and neck cancers." (PMID 31781300, 2019). "Then, Scutellarin also inhibit the proliferation and inhibit the lung and intrahepatic metastasis and migration and invasion of hepatocellular carcinoma in vitro by down-regulating the STAT3/Girdin/Akt signaling." (PMID 30915356, 2019). "Together, these results suggested that IL‐34 contributed to the activation of ERK and STAT3 signal pathways mediated by HBX in hepatoma cells." (PMID 31621133, 2019). "For instance, Signal transducer and activator of transcription 3 (STAT3) is a transcriptional factor which has been reported to activate the transcription of RacGAP1 in hepatocellular carcinoma cells." (PMID 31426369, 2019). "For instance, NC was reported to suppress cell growth via inhibition of the Janus kinase 1 (JAK1)-STAT3 (signal transducer and activator of transcription 3)-signaling pathway in hepatocellular carcinoma." (PMID 30847386, 2019). "In summary, our study demonstrated the preclinical activity of PH, which inhibits hepatic carcinoma in vitro and in vivo and prolonged mouse survival via molecular targeting of STAT3/Akt/mTOR/JAK2/VEGF2 pathways." (PMID 31619257, 2019). "In an analogous system of virally-induced hepatocellular carcinoma, the role of active STAT3 has been suggested in HCV replication." (PMID 31487312, 2019). "Later, it was revealed that it suppresses hepatocellular carcinoma through suppressing the STAT3/HIF-1α/VEGF signaling network." (PMID 30871059, 2019). "We further demonstrated the involvement of the STAT3 pathway in 14–3-3ζ/HO-1 regulation of hepatocellular carcinoma cell proliferation." (PMID 30606233, 2019). "The report about hepatocellular carcinoma demonstrated that IL-6, a CAFs-derived factor, was also reported to play an important role in the functions of dendritic cells through STAT3 signalling." (PMID 31462002, 2019). "CAFs isolated from human hepatic carcinomas were shown to secrete IL-6, which activated STAT3 in DCs, resulting in generation of regulatory DCs." (PMID 31428105, 2019). "Signal transducer and activator of transcription 3 (STAT3) is an important transcriptional factor for cell differentiation, proliferation, and death and is implicated in tumor induced immune suppression in hepatocellular carcinoma (HCC)." (PMID 30046565, 2018). "Investigators have examined p-STAT3 expression among various malignancies such as gastric, renal, and ovarian cancers; squamous cell and hepatocellular carcinoma; and anaplastic large cell lymphoma." (PMID 30123088, 2018).
hepatocellular carcinoma (continued). "C2-ceramide treatment in human hepatocellular carcinoma (HepG2) cells was found to transcriptionally upregulate HAMP mRNA via the JAK/STAT3 signaling cascade." (PMID 30360386, 2018). "Binding of ATF3 to the STAT3 promoter for gene inactivation has also been shown in human hepatocellular carcinoma." (PMID 30455690, 2018). "Mechanistically, we showed that ERO1α prompted angiogenesis, migration, and invasion of hepatoma cells via the S1PR1/STAT3/VEGF-A signaling pathway both in vitro and in vivo." (PMID 30377291, 2018). "Remarkably, miR-197 reduces STAT3 signaling via miR-197/IL-22/STAT3 and miR-197/IL-6/STAT3 pathways in human keratinocytes and hepatocellular carcinomas." (PMID 29890998, 2018). "The IL-6/JAK/STAT3 pathway has been shown to polarize macrophages toward the pro-tumoral M2 phenotype through activation of STAT3, and anti-IL-6 immunotherapy increased the number of M1 polarized macrophages in a hepatocellular carcinoma mouse model." (PMID 30766539, 2018). "In hepatocellular carcinoma, STAT3 binds to the Twist promoter and induces its expression, thus triggering EMT and N-cadherin expression." (PMID 29402970, 2018). "One study reported the secretion of IL6 by the BM-MSCs which activated IL6/Stat3 pathway promoting the invasion of the hepatocellular carcinoma cell line." (PMID 30346985, 2018). "Genistein was shown to upregulate hepcidin in HepG2 hepatoma cells and zebrafish embryos by promoting STAT3 phosphorylation." (PMID 30469435, 2018). "Hsp90 directly interacted with STAT3 via its N-terminal region and the specific Hsp90 inhibitor geldanamycin suppressed IL-6-induced gene expression by interacting with STAT3 in the hepatoma cell line Hep3B." (PMID 29914167, 2018). "Our findings indicate that miR-340-5p directly regulates STAT3 in HBV-mediated promotion of hepatoma cell migration." (PMID 28413603, 2017). "Deletion of SHP-2 dramatically enhanced diethylnitrosamine-induced hepatocellular carcinoma development through the STAT3 pathway." (PMID 28492557, 2017). "The aim of this study is to investigate the effects of stattic (an inhibitor of STAT3) on the radiosensitivity and radio-induced migration and invasion ability in hepatocellular carcinoma (HCC) cell lines." (PMID 29226125, 2017). "As STAT3 reportedly induces the migration of hepatoma cells, we sought to confirm that miR-340-5p inhibits the migration of hepatoma cells by directly regulating STAT3." (PMID 28413603, 2017). "Previous studies have shown IL-6 can regulate the expression of LncTCF7 in hepatocellular carcinoma via a STAT3 pathway." (PMID 28467474, 2017). "Leptin induced STAT3 phosphorylation has also been shown to be inhibited by addition of adiponectin in hepatocellular cancer cells, which is associated with increased suppressor of cytokine signaling 3 (SOCS3) signaling, a negative regulator of STAT3." (PMID 29156726, 2017). "TMED3-mediated IL-11/STAT3 signaling pathway activation was recently reported to participate in tumor progression in hepatocellular carcinoma." (PMID 29100303, 2017). "It is also reported that persistent mTORC1 inhibition can result in elevated inflammation, activation of STAT3 and enhanced hepatocellular carcinoma development." (PMID 29206103, 2017). "Improved understanding the specific role of miR-500a-3p in the activation of STAT3 signaling pathway and in the pathogenesis of hepatocelluar carcinoma facilitates the development of novel therapeutic methods in the treatment of hepatocellular carcinoma." (PMID 28750679, 2017). "Administration of leptin to pancreatic cancer cell lines activates STAT3 signaling, whereas adiponectin inhibits leptin induced phosphorylation of STAT3 in prostate, esophageal and hepatocellular carcinoma cells." (PMID 29156726, 2017). "Recent work has shown that B7-H3 promotes the aggression and invasion of hepatocellular carcinoma by targeting EMT transition via the JAK2/STAT3/Slug signaling pathway." (PMID 29190910, 2017).